STK24 (serine/threonine kinase 24)
Diseases named in the same sentence as STK24 in open-access papers (continued):
Sharing a sentence is not in itself a finding about the gene and the disease.
tumor (continued). "However, the biological function of STK24 in NSCLC tumorigenesis and tumor angiogenesis is still unclear." (PMID 36720310, 2023). "Likewise, deletion of Stk24 in MC38, LLC, and KPC cells of C57BL/6 origin led to significantly delayed tumor development in the immune‐competent C57BL/6 strain, suggesting that STK24 function likely involves in tumor immune response, rather than cell proliferation per se." (PMID 38229183, 2024). "Three independent prognostic DEOSGs (PRODH, STK24, and MAP1LC3A) were identified by multivariate Cox proportional hazards regression analysis after consideration of confounding factors such as gender, tumor, node, and metastasis (TNM) stage, tumor (T) stage, and node (N) stage." (PMID 36180848, 2022). "Interestingly, this tumor showed copy number oscillation compatible with chromothripsis on chromosomes 13, on which FOXO1 and STK24 are located, strongly suggesting that this may be the mechanism underlying the gene fusion." (PMID 30514397, 2018). "Importantly, STK24 depletion does not affect the proliferation of these tumor cells in vitro." (PMID 38229183, 2024). "Besides, the role of STK24 in tumor angiogenesis is not explored in any tumors." (PMID 36720310, 2023). "Consistently, knockdown of Stk24 in CT26, MC38, LLC, and KPC cells did not alter in vitro growth rates in these tumor cells." (PMID 38229183, 2024). "The knock‐down of STK24 in T21A KI CT26 or LLC cells no longer affected tumor growth and tumor weight." (PMID 38229183, 2024).
infection (2 papers, 2018 to 2024). The state of being infected such as from the introduction of a foreign agent such as serum, vaccine, antigenic substance or organism. "Indeed, post-infection time-course RNA-seq analysis showed an upregulation of Casp3 but also a number of other genes involved in apoptosis and necroptosis such as Stk24, Akt1, Madd, Casp7, and Casp8 peaking at 5 and 6 dpi." (PMID 38009950, 2024).
metabolic disorders (1 paper, 2024). "STK24–deficient mice fed a high-fat diet had induced metabolic disorders and insulin insensitivity." (PMID 39327557, 2024).
respiratory diseases (1 paper, 2025). "Previously identified smoking-related CpG sites that were also linked to smoky coal combustion – annotated to genes such as AHRR, SNORD93, NWD1, EDC3, STK24, ZDHHC14, HIF3A – converge on key pathways involved in pollutant response, respiratory diseases, and carcinogenesis." (PMID 40236422, 2025).
STK24 also shares sentences with these, for which no sentence is quoted: Hypertension (8 papers); colorectal cancer (5); hepatocellular carcinoma (4); Obesity (4); Hepatic steatosis (3); Hypokalemia (3); ependymoma (2); Hyperinsulinemia (2); Hypernatremia (2); adenocarcinoma (1); autosomal dominant polycystic kidney disease (1); brain tumor (1); breast tumors (1); cerebral cavernous malformation (1); cervical cancer (1); cholangiocarcinoma (1); colorectal (1); cyst (1); diffuse gastric adenocarcinoma (1); gastric adenocarcinoma (1); gastric intestinal type adenocarcinoma (1); gastric tumor (1); Hyperkalemia (1); inflammation (1); kidney damage (1); Leukaemia (1); liver disease (1); malignant melanoma (1); meningioma (1); Myocardial fibrosis (1).
A further 12 diseases each share a sentence with STK24 in 1 paper.